MIR4712 (microRNA 4712)
Synonyms: hsa-mir-4712
Gene: MicroRNA gene on chromosome 15 (50,360,329 to 50,360,410, forward strand). Ensembl gene ENSG00000284284.
Homologues: Orthologues: chimpanzee MIR4712 (100% identical).